MTOR (mechanistic target of rapamycin kinase)
Diseases named in the same sentence as MTOR in open-access papers (continued):
Sharing a sentence is not in itself a finding about the gene and the disease.
cancer (continued). "PI3K/AKT/mTOR and HIF-1 signaling are central activators of glycolysis and cancer-related metabolism." (PMID 28092669, 2017). "The results suggest that csMVP-associated signaling is mediated through the control of ERK1/2, Akt1/2/3, mTOR and FAK signaling pathways, which are critical for cancer growth, survival and metastasis." (PMID 29038587, 2017). "In order to further confirm the PI3K/mTOR inhibitor to enhance IR-induced cytotoxicity more effectively, we examined cytotoxic effects of IR plus BEZ235 or cisplatin on cancer cells growth." (PMID 28978144, 2017). "There is increasing evidence for an important link between the PI3K/AKT/mTOR pathway and NOTCH1 in sustaining the cancer stem cell niche." (PMID 27980227, 2017). "In this context, three major pro-survival pathways, namely ERK/MAPK, JAK/STAT, and PI3K/Akt/mTOR, concur to increase transcription and translation of HIF1A, especially in cancer." (PMID 29230384, 2017). "And large amount of studies have been focused on the role of mTOR (mammalian TOR) in tumor development and cancer therapies." (PMID 28680431, 2017). "In cancer cells, the main glucose transporter is GLUT1, a facilitative carrier which expression related to the activation of the mTOR pathway—a known target of inhibition by RSV." (PMID 28272357, 2017). "Analyses of the RNA-seq results revealed that cancer cells in both BICA and IVBL exhibited increased expression of mTOR target genes as well as genes involved in cell–cell adhesions." (PMID 28429794, 2017). "Cancer cells became highly invasive and tumorigenic, acquiring stemness properties, and activated AKT/mTOR pathway." (PMID 29156702, 2017). "The enriched genes were involved in pathways commonly found in cancer and stem cells primarily on Focal adhesion, MAPK, Wnt, Notch, Hedgehog, mTOR, and VEGF." (PMID 28717596, 2017). "In cancer cells, autophagy is regulated by phosphatidylinositol 3-kinase (PI3K)/mammalian target of rapamycin (mTOR) and activated protein kinase (AMPK) pathways." (PMID 28771183, 2017). "Most notable amongst the pathways we found were FoxO signalling, mTOR, MAPK signaling, pathways regulating pluripotency of stem cells, TGF-beta signaling and pathways involved in cancer." (PMID 28304372, 2017). "Deregulation of PI3K/protein kinase B (PKB/AKT)/mammalian target of rapamycin (mTOR) (PI3K) pathway and MAPK pathway frequently occurs in human cancers." (PMID 28423582, 2017). "The presence of chronic inflammation in cancer patients has been held responsible for the induction of MDSC via growth factors and cytokines (e.g. G- or GM-CSF, IL-6, TGFβ, PGE2) acting via ERK/mTOR, STAT, NFκB and SMAD signaling pathways." (PMID 28978044, 2017). "NDUFA4L2 and its binding partners participated in growth and death processes and multiple cancer-related KEGG pathways, such as the IGF-1, mTOR (Populo, Lopes & Soares, 2012) and PI3K/AKT signaling pathways." (PMID 29158991, 2017). "Several cancer-related signaling pathways (i.e. Wnt/β-catenin, PI3K/AKT/mTOR, G-protein coupled receptor, and Notch) were affected by the combination therapy, but not by either monotherapy." (PMID 28789624, 2017). "mTOR (mammalian target of rapamycin) signaling is often dysregulated and hyper-activated in HCC, which plays pivotal roles in cancer initiation, progression and chemo-resistance." (PMID 28036295, 2017). "Calorie restriction and associated dietary restriction seem to exert their effects specifically through mTOR, AMPK, and glucose handling (IGF/insulin) pathways with outcomes such as lifespan extension, reduced inflammation and cancer." (PMID 28966808, 2017). "Deregulated nutrient sensing is common to both and interference with the IIS pathway or mTOR pathway and AMP kinase pathway activation increase lifespan and halts cancer." (PMID 28966806, 2017). "mTOR and Unfolded Protein Response (UPR) are two signaling pathways frequently activated in cancer cells." (PMID 28423496, 2017).
cancer (continued). "BRD4, mTOR, IL-1α and additional regulators of SASP are potential targets for anti cancer treatment." (PMID 28966805, 2017). "Inhibition of PI3K/AKT/mTOR signaling by SHR8443 induced G1 phase arrest, autophagy and apoptosis, and resulted in broad anti-proliferative activity against a panel of cancer cells with different genetic backgrounds." (PMID 29296217, 2017). "Sustained and over-activation of mTOR in CRC is positively involved in a number of key oncogenic behaviors, including uncontrolled cancer cell survival, proliferation and migration, as well as chemo-resistance and angiogenesis." (PMID 29221169, 2017). "BEZ235, a novel therapeutic agent that targets two molecules, including PI3K and mTOR in the PI3K/Akt/mTOR pathway, has demonstrated efficacy as an anti-tumour agent in vitro and in vivo in several cancers." (PMID 28060760, 2017). "Preclinical studies testing combinations of PI3K/AKT/mTOR and MEK/ERK pathway-directed inhibitors have shown impressive anti-tumor effects in a variety of cancer subtypes, but these drug combinations have proven toxic in humans." (PMID 28423521, 2017). "Taken together, we propose that a dual targeting approach combining a DYRK1B antagonist with an inhibitor of the PI3K/mTOR/AKT pathway has a pronounced impact on the GLI1 oncoprotein and exerts strong cytotoxic effects in cancer cells." (PMID 27903983, 2017). "Recent researches unveiled that many aberrations centered on certain key pathways of signal transduction in cancer cell, including PI3K/Akt/mTOR and epigenetic alterations." (PMID 28060760, 2017). "The PI3K/AKT/mTOR and the Ras/MEK/ERK pathways are the two major hyper-activated pathways, which promote cell proliferation, survival and metastasis in human cancer." (PMID 28915623, 2017). "In the carcinoma subset, 4 of five patients demonstrated an aberration leading to activation of the PI3K/AKT/mTOR pathway, suggesting that activation of this cascade was more closely associated with this histologic subset when compared to the other 4 subsets." (PMID 28781987, 2017). "Simultaneous inhibition of the mTOR pathway and suppression of the PI3K/Akt survival pathway during CT elicits a stronger inhibition of cancer cells than CT alone." (PMID 27486756, 2016). "To study the function of 4E-BP3 downstream of mTORC1, we examined the effect of mTOR inhibitors (rapamycin, or asTORi, INK1341 and PP242) on the expression of 4E-BP3 in a panel of human cancer cell lines." (PMID 27319316, 2016). "Cancer cells take advantage of these pathways to further extend their survival advantages, such as activated PI3K/AKT/mTOR pathways, which can activate HIF-1α as previously discussed." (PMID 26962408, 2016). "We found that suppressing the mTOR pathway using either everolimus or metformin led to suppression of TNT formation in vitro, verifying TNTs as a potential target for cancer-directed therapy." (PMID 27223082, 2016). "For example, activation of the mTOR signaling pathway promotes, while blocking this pathway inhibits, EMT, cell migration, invasion, and cancer metastasis." (PMID 27174914, 2016). "It is known that BCPO alters several key pathways for cancer development, such as mitogen‐activated protein kinase (MAPK), PI3K/AKT/mTOR/S6K1 and STAT3 pathways." (PMID 27696789, 2016). "miR-7 inhibits tumorigenesis and cancer metastasis in hepatocellular carcinoma by blocking PIK3CD, mTOR, and p70S6K." (PMID 27187382, 2016).
cancer (continued). "Initial studies using rapamycin to verify the involvement of mTOR signaling for tumorigenic formation of CSCs that were discussed previously provided a convincing basis that targeting the mTOR pathway using inhibitors may eradicate CSCs which can in turn augment overall cancer treatment." (PMID 27826244, 2016). "In summary, mTOR, PI3K, HIF and MYC are key regulators of cellular metabolism that are frequently altered in cancer, collaborating in both synergistic and antagonistic ways." (PMID 28040803, 2016). "Furthermore, PEE treatment could inhibit the expression of mTOR phosphorylated at S2448, which is the catalytic subunit of mTORC1 complex and thus might interfere with the nutrient metabolism or energy production in cancer cell." (PMID 26955879, 2016). "It is known that BCPO alters several key pathways for cancer development, such as MAPK, PI3K/AKT/mTOR/S6K1, and STAT3 pathways." (PMID 27696789, 2016). "With this approach, we predict prognosis and response to chemotherapy in cancer patients, and screen for potential pharmacological modulators of PI3K-Akt-mTOR pathway inhibitors." (PMID 27589846, 2016). "The PI3K/Akt pathway is frequently activated in many cancers, and previous studies have revealed a convergence of PI3K/Akt/mTOR activation through a variety of mechanisms in clear RCC." (PMID 27816967, 2016). "In conclusion, our studies reveal an important signaling mechanism that phycocyanin induces apoptotic and autophagic cancer cell death via balancing the complex regulation of the MAPK, Akt/mTOR and NF-κB signaling pathways." (PMID 27694919, 2016). "Regulation of autophagy by several protein kinases including mTOR, Akt, and ERK, is an important therapeutic target for promoting cell survival and preventing cancers and other diseases." (PMID 27070587, 2016). "To examine the mechanistic basis of Ets2 in ESCC, we determined the effects of Ets2 knockdown on the expression of phosphorylated mTOR (p-mTOR), p70S6K and Prdx1 of ESCC cell in vitro and cancer xenograft mouse model." (PMID 27556183, 2016). "LKB1, AMPK and mTOR pathways regulate many important cellular processes, such as cell regulation of cell cycle, proliferation, energy homeostasis, migration and EMT in cancer." (PMID 27150059, 2016). "This has important implications for planned trials of these compounds in pediatric cancer, since multiple PI3K, mTOR and dually targeted PI3K/mTOR drugs are already in active clinical evaluation." (PMID 27438153, 2016). "KEGG pathway analysis showed that target genes were enriched in the cancer pathway, as well as other pathways related to hair follicle development such as the Wnt, TGF-β, MAPK, and mTOR signaling pathways." (PMID 27404636, 2016). "YBX-1 can activate E2F, PI3K/Akt/mTOR and Ras/Raf/MEK/ERK pathways to promote cancer cell proliferation." (PMID 26805816, 2016). "A recent study established that GOLPH3 has oncogenic properties mediated via mTOR signaling, and that GOLPH3 gene at 5p13 region is frequently amplified in a number of cancers." (PMID 27706081, 2016). "The results suggest that these miRNAs-regulated pathways involve cancer-related pathways, such as ‘MAPK signaling pathway’, ‘adherens junction’, ‘calcium signaling pathway’, ‘focal adhesion’ and ‘mTOR signaling pathway’." (PMID 27013589, 2016). "The phosphatidylinositol 3-kinase/protein kinase-B/mammalian target of rapamycin (PI3K/AKT/mTOR) signalling cascade is a key oncogenic signalling pathway, which has a central role in several cellular processes significant for cancer progression." (PMID 27713912, 2016). "These compounds also possess anti-proliferative effects on cancer cells and have similar IC50 values toward mTOR as the Torin and Ku compounds and have reasonable selectivity for mTOR as compared to the PI3Ks (approximately 100-fold)." (PMID 27635236, 2016).
cancer (continued). "Given the importance of mTOR pathway, not only in ALK-related cancer, targeted therapy aimed to block its dysregulated downstream signaling has been widely investigated." (PMID 27662658, 2016). "Statins are known to reduce cell proliferation via down-regulation of critical signaling pathways in a few human cancers, including AKT/mTOR, MAPK, JAK2/STAT3, Ras, NF-κB, JUNK and RhoA/ROCK pathways." (PMID 26503475, 2016). "ESCC is a common cancer in China and had high mortality rate; we have conducted some previous studies about the mTOR pathway in ESCC and demonstrated the activation of mTOR pathway in ESCC." (PMID 27595116, 2016). "It is well known that in cancer cells, autophagy was negatively regulated by mTOR, which is positive mediated by PI3K/AKT pathway and a major regulator of cell growth in human cancers." (PMID 26808193, 2016). "Infection of mesenchymal MDA-MB-231 cancer cells with Ad-E1A12 also resulted in dramatic activation of AKT and mTOR signaling." (PMID 27849011, 2016). "The carcinogenic activity of DJ-1 regulates mTOR and AMPK functions as activated factor of HIF1 upstream function of cancer cells." (PMID 27020667, 2016). "The MAPK, mTOR, and NF-kB signaling pathways have all been reported to control VEGF-C expression by cancer cells." (PMID 26950548, 2016). "mTOR is a known negative regulator of autophagy, whereas CDDP induces antitumorigenic autophagy in cancer cells." (PMID 26800397, 2016). "In summary, a PI3K pathway inhibitor cancer cell line screen identified the hematological malignancy subtype as being the most sensitive to AKT and mTOR inhibition." (PMID 26989080, 2016). "Given that 3-AWA inhibits c-FLIP through abrogation of translation initiation by co-targeting mTOR and Mnk-eIF4E, it (3-AWA) can be exploited as a lead pharmacophore for promising anti-cancer therapeutic development." (PMID 26728896, 2016). "mTOR functions both in parallel and downstream of the PI3K/AKT signaling pathway that is frequently dysregulated in cancer and a subject of intense discovery research." (PMID 27015560, 2016). "In various cancers, proteins from the phosphatidylinositol 3-kinase (PI3K)/AKT/mTOR signaling pathway are found altered, and have been correlated with autophagy regulation." (PMID 26735175, 2016). "Several groups reported that TERT can form a complex with mTOR and other proteins such as PI3K/Akt, Hsp90 and S6 kinase in cancer cells." (PMID 27777385, 2016). "Growing evidence has suggested that the phosphatidylinositol 3-kinase (PI3K)/AKT/mammalian target of rapamycin (mTOR) pathway, wherein MDR1 and NF-kappaB are downstream factors of this pathway, is closely related to the occurrence of drug resistance in cancer." (PMID 27293459, 2016). "Multiple signaling pathways, such as PI3K/Akt/mTOR, mitogen-activated protein kinase, and Wnt/β-catenin, are activated by EGFR to enhance proliferation, survival, invasion, and metastasis of cancer cells." (PMID 27034004, 2016). "The effectiveness of mTOR inhibition in suppressing TNT formation represents a potentially novel and complementary approach to cancer-directed therapy." (PMID 27223082, 2016). "Since mTOR inhibitor- induced eIF4E phosphorylation is PI3K and Mnk dependent, one strategy to improve an mTOR inhibitor’s efficacy against cancer is to prevent eIF4E phosphorylation by combining an mTOR inhibitor with a PI3K inhibitor or a Mnk inhibitor." (PMID 26728896, 2016). "In cancer cells, the suppression of PI3K/AKT/mTOR pathway and the upregulated protein level of Beclin-1 are consistently connected with the induction of autophagy." (PMID 26808193, 2016).
cancer (continued). "Semiquantitative evaluation revealed that the elevated expression of pAKT1, MTOR, pEIF4EBP1 and SLC2A1 in cancer was evident in 47 (94%), 30 (60%), 43 (86%) and 42 (84%) cases, respectively." (PMID 27512993, 2016). "Alternatively, it has also been demonstrated that there is a crosstalk between PI3K/AKT/mTOR pathway and the RAS/RAF/MEK/ERK pathway in cancers." (PMID 27119232, 2016). "In many cancers, the PI3K/Akt/mTOR pathway is overactive, preventing apoptosis and supporting uncontrollable proliferation." (PMID 27070592, 2016). "Recent studies have documented the functional link between c-Myc and mTOR in regulating protein synthesis, suggesting that mTOR-dependent phosphorylation of 4E-BP1 is necessary to cancer cell survival in c-Myc-dependent tumor initiation and maintenance." (PMID 27769069, 2016). "Some HIF-1α upstream regulatory molecules such as NOTCH, mTOR (mechanistic target of rapamycin) and LKB1 can also regulate LOX expression indirectly through HIF-1α and mediates cancer progression." (PMID 28036074, 2016). "The found discriminant isoforms are enriched for multiple cancer hallmarks, including EMT and the mTOR pathway." (PMID 27535130, 2016). "The miRNA-99 family's modulation of the PI3K/mTOR signaling pathway and IGF-1R signaling have been observed in a number of cancers, supporting their role in modulating proliferation, migration, and apoptosis." (PMID 27840833, 2016). "Previous work established that in cancer cell lines, excess PI3K pathway signaling modulates the AKT-regulated targets GSK3β and mTOR, extending the half-life of MYC and outlining a potential pharmacologic approach for targeting MYC stability." (PMID 27438153, 2016). "It is well known that the PI3K/AKT/mTOR and MEK/ERK pathways can directly and effectively promote cancer cell proliferation, migration and invasion, while inhibiting the apoptosis of tumor cells." (PMID 27556696, 2016). "In this study, we identified p70S6K activation by IL-6 located downstream of the PI3K/Akt/mTOR, MAPK/ERK, and JAK/STAT3 signaling pathways, which were the most important survival pathways that promote most cancers." (PMID 27174914, 2016). "The PI3K/Akt/mTOR and MAPK/ERK signaling pathways are acknowledged as the main signaling pathways that mediate IL-6's stimulating effect in many cancer types." (PMID 27174914, 2016). "Mmu-miR-505-5p was downregulated in Sca-1+CD31− compared to Sca-1+CD31+ cells, with targets Cyp1b1, Dcbld2, Igf1, and Ppp1r14b,Txndc5 increased in expression; Igf1 was involved in mTOR and PI3K-Akt signaling and Cyp1b1by with microRNAs in cancer." (PMID 27298624, 2016). "Blockage of mTOR by AMPK triggers autophagy, which acts a pro-survival role for cancer cells during ECM detachment." (PMID 26910278, 2016). "This specific Akt inhibitor allows inhibition of both PI3K/Akt/mTOR and MAPK pathway at once, and subsequently inhibition of cancer cell proliferation." (PMID 27626684, 2016). "Across cancer types, the degree to which metformin relies upon AMPK activation to inhibit growth and alter mTOR/p70S6K signaling is unclear and likely cell type-dependent." (PMID 26760500, 2016). "Based on the result of the IPA analysis, 5 proteins (TGFβ1, PI3K, Akt, mTOR and PTEN) related to specific functions, such as proteins synthesis, cellular functionsand cancer, were selected for verification." (PMID 25793716, 2015). "In matched tumour-normal patient cancer samples, we observed a striking correlation between PRL-3 expression and the ratio of phosphorylated/total 4E-BP1, a bona fide readout of PI3K/Akt/mTOR pathway activity." (PMID 26597054, 2015).